PF4 (platelet factor 4)
Description:
Chemokine released during platelet aggregation that plays a role in different biological processes including hematopoiesis, cell proliferation, differentiation, and activation. Acts via different functional receptors including CCR1, CXCR3A or CXCR3B. Upon interaction with CXCR3A receptor, induces activated T-lymphocytes migration mediated via downstream Ras/extracellular signal-regulated kinase (ERK) signaling. Neutralizes the anticoagulant effect of heparin by binding more strongly to heparin than to the chondroitin-4-sulfate chains of the carrier molecule. Plays a role in the inhibition of hematopoiesis and in the maintenance of hematopoietic stem cell (HSC) quiescence. Chemotactic for neutrophils and monocytes via CCR1. Inhibits endothelial cell proliferation. In cooperation with toll-like receptor 8/TLR8, induces chromatin remodeling and activates inflammatory gene expression via the TBK1-IRF5 axis. In addition, induces myofibroblast differentiation and collagen synthesis in different precursor cells, including endothelial cells, by stimulating endothelial-to-mesenchymal transition. Interacts with thrombomodulin/THBD to enhance the activation of protein C and thus potentiates its anticoagulant activity.
Synonyms: PF-4; CXCL4; SCYB4
Tractability: Small molecule: a structure with a bound ligand is known; it has a high-quality binding pocket. Antibody: UniProt places it where antibodies can reach, with high confidence; its Gene Ontology location is reachable by antibodies, with high confidence; UniProt predicts a signal peptide or a membrane-spanning region. PROTAC: its protein half-life has been measured; a small molecule that binds it is known.
Target class: Secreted protein
Gene: Protein-coding gene on chromosome 4 (73,980,811 to 73,982,027, reverse strand). Ensembl gene ENSG00000163737.
Subcellular location: Secreted
Pathways (Reactome):
Hemostasis: Cell surface interactions at the vascular wall; Platelet degranulation; Regulation of clotting cascade
Signal Transduction: Chemokine receptors bind chemokines; G alpha (i) signalling events
Gene expression (Transcription): RUNX1 regulates genes involved in megakaryocyte differentiation and platelet function
Gene Ontology:
Molecular function: chemokine activity; CXCR3 chemokine receptor binding; heparin binding; protein binding; receptor ligand activity; CXCR chemokine receptor binding
Biological process: adenylate cyclase-activating G protein-coupled receptor signaling pathway; antimicrobial humoral immune response mediated by antimicrobial peptide; cytokine-mediated signaling pathway; defense response to protozoan; leukocyte chemotaxis; monocyte chemotaxis; negative regulation of angiogenesis; negative regulation of blood coagulation; negative regulation of extrinsic apoptotic signaling pathway in absence of ligand; negative regulation of megakaryocyte differentiation; negative regulation of MHC class II biosynthetic process; platelet activation; positive regulation of gene expression; positive regulation of macrophage derived foam cell differentiation; positive regulation of macrophage differentiation; positive regulation of transcription by RNA polymerase II; positive regulation of tumor necrosis factor production; regulation of cell population proliferation; cellular response to lipopolysaccharide; inflammatory response; neutrophil chemotaxis; chemotaxis; defense response; immune response
Cellular component: cytoplasm; extracellular matrix; extracellular region; platelet alpha granule lumen
Genetic constraint (gnomAD): Loss-of-function variants: 10 observed, 7.4 expected, observed/expected ratio (o/e) 1.35, 90% interval 0.81 to 1.9. That is too few expected variants to judge how well the gene tolerates losing a copy. Missense variants: 110 observed, 122.1 expected, observed/expected ratio (o/e) 0.9, 90% interval 0.77 to 1.06. Synonymous variants: 55 observed, 56.35 expected, observed/expected ratio (o/e) 0.98, 90% interval 0.79 to 1.22.
Homologues: Orthologues: chimpanzee PF4 (98% identical), macaque PF4 (93% identical). Paralogues in human: PF4V1 (86% identical), PPBP (43% identical), CXCL1 (40% identical), CXCL5 (39% identical), CXCL6 (38% identical), CXCL2 (37% identical), CXCL3 (35% identical), CXCL8 (27% identical), CXCL9 (26% identical), CXCL10 (25% identical), CXCL13 (24% identical), CXCL11 (23% identical).
Diseases named in the same sentence as PF4 in open-access papers:
PF4 is named in the same sentence as 302 diseases in open-access papers, as found by Europe PMC text mining. Sharing a sentence is not in itself a finding about the gene and the disease. The quoted sentences say what the papers report.
Thrombocytopenia (275 papers, 2008 to 2026). A reduction in the number of circulating thrombocytes. "The clinical suspicion of an anti-PF4 immune disorder should be considered in cases of severe, otherwise unexplained, thrombotic events associated with thrombocytopenia." (PMID 41594233, 2026). "The two-step mechanism underlying VITT is similar to the pathogenesis of heparin-induced thrombocytopenia, with both conditions caused by antiplatelet factor 4 (PF4) antibodies." (PMID 40226433, 2025). "Chronic VITT-like anti-PF4 antibodies causing recurrent thrombosis and thrombocytopenia are often linked to monoclonal gammopathies." (PMID 40236285, 2025). "Anti‐PF4 mediated thrombocytopenia and thrombosis associated with acute cytomegalovirus infection displays both HIT‐like and VITT‐like characteristics." (PMID 40289696, 2025). "These entities are characterized by a common pathogenic mechanism involving the formation of antibodies directed against PF4 tetrameric complexes, liable to produce a prothrombotic coagulopathy associated with thrombocytopenia." (PMID 41302191, 2025). "More recently, some novel clinical-pathological anti-PF4-associated entities also characterized by thrombosis, thrombocytopenia, and VITT-like antibodies but independent from heparin or AdV-vaccine administration have been identified." (PMID 40573981, 2025). "Heparin-induced thrombocytopenia (HIT) is classified into Type 1, a benign, non-immune reaction resolving spontaneously, and Type 2, a severe immune-mediated disorder caused by anti-PF4-heparin antibodies, leading to thrombocytopenia and thrombosis." (PMID 40276517, 2025). "Recent literature describes these atypical presentations of anti-PF4 disorders primarily in adult patients, although adenoviral-associated thrombocytopenia and thrombosis have been reported in both pediatric and adult patients." (PMID 39759125, 2025). "This review focuses on type II HIT, characterized by the development of antibodies against platelet-factor 4 (PF4) bound to heparin after exposure, causing life-threatening thrombocytopenia, arterial thrombosis, and/or venous thrombosis." (PMID 39200826, 2024). "Heparin-induced thrombocytopenia is associated with the presence of antibodies that recognize complexes of PF4 and heparin." (PMID 39575034, 2024). "Prothombotic anti-PF4/polyanion autoantibodies associated with thrombocytopenia are implicated in pathogenesis of cerebral malaria in children." (PMID 38652559, 2024). "PF4-dependent platelet activation induced by CM patient plasma is associated with anti–PF4/P IgG levels and thrombocytopenia." (PMID 38652559, 2024). "Both VITT and HIT disorders are associated with thrombocytopenia, thrombosis, the presence of autoantibodies to PF4, and platelet activation through platelet FcγRIIa." (PMID 38034388, 2023). "Heparin-induced thrombocytopenia, which results from production of antibodies that bind to heparin-platelet factor 4 (PF4) complexes, is a hypercoagulable state associated with considerable morbidity and mortality due to thrombotic complications." (PMID 37907435, 2023). "VITT often presents with thrombosis at unusual sites such as cerebral venous sinuses, portal, splanchnic or hepatic veins, in association with thrombocytopenia and elevated anti-platelet factor 4 (aPF-4) antibodies." (PMID 36741657, 2023). "The mechanism of this phenomenon has been clarified and seems to be linked to the presence of a transitory thrombocytopenia vaccine induced by the development of autoantibodies against platelet factor 4 (PF4)." (PMID 37238951, 2023). "Platelet Factor 4 reactive antibodies-mediated response consistent with heparin-induced thrombocytopenia was also reported by the authors, and clinically associated with exposure to the vaccine." (PMID 35368622, 2022).
Thrombocytopenia (continued). "The production of PFA autoantibodies induces platelet activation through the formation of PF4-polyanion complexes, causing thrombocytopenia, disseminated intravascular coagulation, and atypically located thrombotic events." (PMID 35214765, 2022). "Thrombocytopenia is caused by rogue antibodies directed against platelet factor 4 (PF4), which causes massive platelet aggregation and thrombosis and a reduction in the platelet count resulting in bleeding." (PMID 35582622, 2022). "Recently, the PLT proteome from patients with Dengue Virus, where thrombocytopenia is a hallmark, showed alterations in protein expression (e.g., PF4/CXCL4 and HLA class I proteins associated with antigen processing and presentation)." (PMID 34991449, 2022). "TTS-CVST requires specific regimens of anticoagulation and immunomodulation therapy if thrombocytopenia and/or pathogenic antibodies to PF4/polyanion complexes are present." (PMID 35184205, 2022). "The thrombosis is likely caused in a way similar to heparin‐induced thrombocytopenia; platelet‐activating antibodies against PF4 produced after vaccination; hence, laboratory tests are needed for definitive diagnosis." (PMID 35846901, 2022). "These events were reported mostly in women of childbearing age, associated with thrombocytopenia and antibodies against platelet factor-4 (PF-4), referred to as vaccine-induced thrombotic thrombocytopenia (VITT)." (PMID 35215771, 2022). "Vaccine-induced CVST-TTS requires specific anticoagulation and immunomodulation therapies, especially in the case of thrombocytopenia and/or the detection of pathogenic antibodies against PF4/polyanion complexes." (PMID 35184205, 2022). "One year ago, thromboses in Vaxzevria recipients have been associated with thrombocytopenia in the presence of antibodies to platelet factor 4 and have been called vaccine-induced immune thrombotic thrombocytopenia (VITT)." (PMID 36247442, 2022). "These anti-PF4/H antibodies can pathologically activate platelets in a proportion of susceptible patients, leading to platelet aggregation, associated thrombocytopenia, and thrombosis at sites of vessel occlusion." (PMID 35225866, 2022). "The hallmarks of HIT are antibodies specific for the heparin/platelet factor 4 (PF4) complex that cause thrombocytopenia and thrombosis through platelet activation." (PMID 34639132, 2021). "Vaccine-induced thrombotic thrombocytopenia (VITT) is characterized by thrombocytopenia and thrombosis in association with anti-platelet factor 4 (PF4) antibodies." (PMID 35095856, 2021). "Data are needed to confirm that the anti-PF4 antibodies described here can cause thrombosis and thrombocytopenia in vivo." (PMID 34443589, 2021). "Alternatively, Ads have been shown to activate platelets in the bloodstream and induce thrombocytopenia, potentially causing a release of PF4 and leading to the induction of anti-PF4 antibodies." (PMID 34354082, 2021). "Mechanisms of PF4/heparin antibody binding, involvement in pathogenesis of heparin-induced thrombocytopenia, and involvement in HIT-associated thrombosis of various cell types." (PMID 35126147, 2021). "The association was based on the presence of thrombocytopenia, anti-platelet factor 4 antibodies, and multiple organ thrombosis (vaccine-induced immune thrombotic thrombocytopenia (VITT))." (PMID 34535076, 2021). "The role of anti-platelet factor-4 antibodies seem causative, inducing platelet activation, aggregation, and thrombosis, leading to a severe platelet consumption and thrombocytopenia." (PMID 34535076, 2021). "The presence of thrombocytopenia is useful but if the anamnesis reveals a further cause of possible thrombocytopenia, a dosage of anti-PF4-Hep is required to improve the acquisition of data for a fast diagnosis of VITT." (PMID 34684034, 2021).
Thrombocytopenia (continued). "It is characterized by thrombocytopenia and anti-PF4 IgG antibodies and has been associated with administration of non-replicating viral vector vaccines (AstraZeneca and Janssen/Johnson & Johnson vaccines)." (PMID 34572349, 2021). "Arepally and colleagues identified that the murine monoclonal antibody KKO forms PF4/heparin complexes and causes heparin-induced thrombosis and thrombocytopenia in a murine model, thus classifying KKO as a pathogenic antibody." (PMID 33050376, 2020). "HIT can be classified as both an immune-mediated disorder as well as a consumptive thrombocytopenia; this is because the pathogenic anti-platelet factor 4 (PF4)/heparin antibodies activate platelets and trigger an associated procoagulant response." (PMID 31121897, 2019). "The hallmark of HIT is antibodies to the heparin/platelet factor 4 (PF4) complex that cause thrombocytopenia and thrombosis through platelet activation." (PMID 31263574, 2019). "While sepsis caused thrombocytopenia, the remaining circulating platelets were activated as demonstrated by increased p-selectin expression, elevated plasma PF4, and enhanced platelet-leukocyte aggregate formation compared to Sham animals." (PMID 29617417, 2018). "Diagnostic criteria of HIT include onset of thrombocytopenia within 5–14 days of heparin exposure along with detection of platelet-activating anti-PF4/heparin antibodies, while overt thrombosis is seen in up to 50% of cases." (PMID 28698883, 2017). "The appearance of heparin-dependent anti-PF4 antibodies is associated with thrombocytopenia, while the appearance of heparin-independent anti-PF4 antibodies is related to SLE disease activity." (PMID 27699076, 2016). "Heparin-induced thrombocytopenia is caused by antibodies (Abs) specific to platelet factor 4 (PF4)/heparin complexes." (PMID 27558507, 2016). "Dengue infection is associated with thrombocytopenia, a positive tourniquet test, and release of platelet contents, including platelet factor 4 (PF4), into the circulation." (PMID 24444080, 2014). "Heparin-induced thrombocytopenia is an immune-mediated serious adverse effect of heparin therapy caused by IgG antibodies against heparin/platelet factor 4 (PF4) complexes, resulting in thrombocytopenia associated with thromboembolic events." (PMID 25013684, 2014). "Studies have shown that only the IgG class of anti-PF4/heparin antibodies are platelet-activating and thus have the potential to cause heparin-induced thrombocytopenia." (PMID 23646121, 2013). "HIT is caused by the generation of heparin-dependent antibodies against the PF4/heparin complex, which cause platelet activation and aggregation and eventually progress to thrombocytopenia and thrombosis." (PMID 21261941, 2011). "Consequently, the clinical insights gained from VITT remain pertinent: thrombosis associated with thrombocytopenia and significantly elevated D-dimer levels, particularly following viral infection, should be investigated and managed as anti-PF4 disease." (PMID 41295485, 2025). "The patient continues to suffer from chronic ischemic neuropathy, with uncertainty regarding the cause of ongoing thrombocytopenia—whether due to persistent anti-PF4 antibodies, underlying conditions, or lifestyle factors like alcohol consumption." (PMID 41295485, 2025). "One theory suggests that this could be related to the heparin-induced thrombocytopenia phenomenon, where platelet activation involves anti-PF4 antibodies that are associated with thrombosis." (PMID 39287233, 2024). "As reported by study’s authors, patients developing a new-onset headache should be carefully monitored for the risk of developing cerebral venous thrombosis, especially those with risk factors, such as thrombocytopenia, anti-platelet factor 4 antibodies, and multiple organ thrombosis." (PMID 37445269, 2023).
Thrombocytopenia (continued). "Although PF4 is present in platelets at unusually high concentrations, thrombocytopenia, a hallmark of sepsis and other infections, may deplete the pool of PF4, resulting in the loss of its protective function." (PMID 37868353, 2023). "Heparin-induced thrombocytopenia antibodies or anti-platelet factor 4 (anti-PF4) antibodies have been identified as pathogenic antibodies by enzyme-linked immunosorbent assays (ELISAs), which have also detected anti-PF4/polyanion immunoglobulin G (IgG) antibodies." (PMID 36992276, 2023). "HIT, particularly type 2, is an autoimmune-like reaction in which antibodies bind to platelet factor 4 (PF4)/heparin complexes that activate platelets via their FcγIIa receptors, resulting in thrombocytopenia, hypercoagulability, and greatly increased risk of arterial or venous thrombosis." (PMID 36639796, 2023). "Moreover, we also provided insight into the potential role of the ontogeny of the two platelet proteins, GPVI and PF4, implicated in platelet activation, possibly leading to thrombocytopenia." (PMID 37111598, 2023). "It remains uncertain whether the majority of thrombotic events in the early post-vaccination period are associated with thrombocytopenia and PF-4 antibodies." (PMID 35215771, 2022). "In the present study, IgG antibodies to PF4 alone were associated with a more severe and persistent thrombocytopenia, suggesting they could accelerate platelet clearance." (PMID 35971886, 2022). "Anti-PF4 antibodies, which mimic heparin-induced thrombocytopenia-like disease, cause platelet activation and may induce thrombosis in rare cases." (PMID 35214742, 2022). "Notably, COVID-19 vaccination can cause thrombosis and thrombocytopenia through a mechanism related to the production of pathologic antibodies to platelet factor 4 (PF4), leading to systemic venous thrombosis." (PMID 35632556, 2022). "Both infection and vaccination are associated with PF4-mediated thrombocytopenia." (PMID 35159235, 2022). "Studies on the side effects of the ChAdOx1 nCOV‐19 vaccine suggested that it can induce an immune reaction similar to that of heparin‐induced thrombocytopenia (HIT) by producing autoantibodies to PF4–polyanion complex, which activates the platelets, thus, causing thrombosis and thrombocytopenia." (PMID 35769629, 2022). "Supporting this hypothesis is a recent study identifying platelet-activating anti-PF4 antibodies in the sera of patients suffering from unusual thrombotic events associated with thrombocytopenia within 4 to 16 days after receiving Vaxzevria." (PMID 34443589, 2021). "From preliminary data obtained they proposed a sequence of post-vaccine inflammatory responses in the VITT patients reminiscent of autoimmune HIT that may have triggered the induction of anti-PF4 Abs that caused prothrombotic reactions and thrombocytopenia." (PMID 34557868, 2021). "However, no clear cause-effect relationship has been established between thrombocytopenia and macrothrombosis, as well as thrombocytopenia and anti-PF4 antibodies." (PMID 34833382, 2021). "Both infection and vaccination are associated with a PF4-mediated thrombocytopenia." (PMID 34290613, 2021). "HIT II is a serious side effect of heparin that may cause thrombocytopenia and thromboembolism when platelet factor 4/heparin complex and HIT antibody form an immune complex to activate blood platelets." (PMID 32026037, 2020). "Diseases associated with PF4 included thrombocytopenia and megakaryocytic leukemia." (PMID 30881521, 2019). "Thus HIT antibodies develop and function to cause thrombocytopenia and/or thrombosis only in the presence of PF4." (PMID 23561460, 2013). "Moreover, a typical VITT-like syndrome with CVST, thrombocytopenia, and hyperfibrinolysis was reported in a female neonate due to transplacental transfer of maternal platelet-activating prothrombotic anti-PF4 IgG that had caused pulmonary embolism in a previous pregnancy 18 months before." (PMID 40573981, 2025).